OR7E24 (olfactory receptor family 7 subfamily E member 24)
Description:
Odorant receptor.
Synonyms: OR7E24P; OR19-8; HSHT2; OR7E24Q
Tractability: Antibody: UniProt places it where antibodies can reach, with medium confidence; UniProt predicts a signal peptide or a membrane-spanning region; its Gene Ontology location is reachable by antibodies, with medium confidence.
Gene: Protein-coding gene on chromosome 19 (9,247,344 to 9,252,625, forward strand). Ensembl gene ENSG00000237521.
Subcellular location: Cell membrane
Pathways (Reactome):
Sensory Perception: Expression and translocation of olfactory receptors
Gene Ontology:
Molecular function: olfactory receptor activity; G protein-coupled receptor activity
Biological process: signal transduction; detection of chemical stimulus involved in sensory perception of smell; G protein-coupled receptor signaling pathway
Cellular component: plasma membrane; membrane
Genetic constraint (gnomAD): Loss-of-function variants: 0 observed, 0.38 expected, observed/expected ratio (o/e) 0, 90% interval 0 to 1.85. That is too few expected variants to judge how well the gene tolerates losing a copy. Missense variants: 376 observed, 419.87 expected, observed/expected ratio (o/e) 0.9, 90% interval 0.82 to 0.98. Synonymous variants: 130 observed, 159.4 expected, observed/expected ratio (o/e) 0.82, 90% interval 0.71 to 0.94.
Homologues: Orthologues: macaque OR7E24 (93% identical), dog OR7E153 (74% identical), mouse Or7e177 (68% identical), rat Or7e176b (63% identical), mouse Or7e176 (63% identical), mouse Or7e175 (63% identical), mouse Or7e173 (62% identical), mouse Or7e174 (62% identical), rat Olr1177 (62% identical), rat Or7e173d (62% identical), rat Or7e176 (62% identical), rat Or7e174 (61% identical), and 1 more. Paralogues in human: OR7D4 (60% identical), OR7A17 (58% identical), OR7C2 (58% identical), OR7A5 (57% identical), OR7A10 (57% identical), OR7C1 (56% identical), OR7G3 (55% identical), OR7D2 (55% identical), OR7G2 (55% identical), OR7G1 (52% identical), OR1G1 (50% identical), OR1E1 (49% identical), and 116 more.
Diseases named in the same sentence as OR7E24 in open-access papers:
OR7E24 is named in the same sentence as 4 diseases in open-access papers, as found by Europe PMC text mining. Sharing a sentence is not in itself a finding about the gene and the disease. The quoted sentences say what the papers report.
glioblastoma (1 paper, 2021). The most malignant astrocytic tumor (WHO grade IV). "Aberrations and subsequent abnormal expression of OR7E24 have been observed in glioblastoma, hepatocellular carcinoma, and stomach cancer, with an association with microsatellite instability and high tumor mutational burden in the latter." (PMID 33431066, 2021).
OR7E24 also shares sentences with these, for which no sentence is quoted: tumor (2 papers); hepatocellular carcinoma (1); stomach cancer (1).